CARMIL2 (capping protein regulator and myosin 1 linker 2)
Description:
Cell membrane-cytoskeleton-associated protein that plays a role in the regulation of actin polymerization at the barbed end of actin filaments. Prevents F-actin heterodimeric capping protein (CP) activity at the leading edges of migrating cells, and hence generates uncapped barbed ends and enhances actin polymerization. Plays a role in cell protrusion formations; involved in cell polarity, lamellipodial assembly, membrane ruffling and macropinosome formations. Involved as well in cell migration and invadopodia formation during wound healing. Required for CD28-mediated stimulation of NF-kappa-B signaling, involved in naive T cells activation, maturation into T memory cells, and differentiation into T helper and T regulatory cells.
Synonyms: LRRC16C; RLTPR; CARMIL2b; IMD58
Tractability: Antibody: UniProt places it where antibodies can reach, with high confidence; its Gene Ontology location is reachable by antibodies, with high confidence. PROTAC: ubiquitination databases record sites on it.
Gene: Protein-coding gene on chromosome 16 (67,644,988 to 67,657,569, forward strand). Ensembl gene ENSG00000159753.
Subcellular location: Cytoplasm (Isoform 2); Cytoplasm, cytoskeleton; Cell membrane; Cell projection, lamellipodium; Cell projection, ruffle
Gene Ontology:
Molecular function: phospholipid binding; protein-containing complex binding
Biological process: actin filament network formation; establishment or maintenance of cell polarity; establishment or maintenance of monopolar cell polarity; negative regulation of barbed-end actin filament capping; positive regulation of cell migration; positive regulation of extracellular matrix disassembly; positive regulation of lamellipodium assembly; positive regulation of lamellipodium organization; positive regulation of ruffle assembly; wound healing, spreading of cells; cell migration; regulation of Arp2/3 complex-mediated actin nucleation
Cellular component: actin cytoskeleton; cell leading edge; cytoplasm; intermediate filament cytoskeleton; lamellipodium; macropinosome; membrane; plasma membrane; ruffle; extrinsic component of cytoplasmic side of plasma membrane; cytoskeleton
Genetic constraint (gnomAD): Loss-of-function variants: 93 observed, 157.62 expected, observed/expected ratio (o/e) 0.59, 90% interval 0.5 to 0.7. The upper end of that interval is the gene's LOEUF score, 0.7, which puts it in group 2 of 6, group 1 being the genes least tolerant of losing a copy. Missense variants: 1,719 observed, 1,792.9 expected, observed/expected ratio (o/e) 0.96, 90% interval 0.92 to 1. Synonymous variants: 800 observed, 773.79 expected, observed/expected ratio (o/e) 1.03, 90% interval 0.98 to 1.1.
Gene-disease validity (ClinGen):
ClinGen rates the evidence that CARMIL2 causes each of these diseases.
severe combined immunodeficiency due to CARMIL2 deficiency (autosomal recessive): Definitive.
Homologues: Orthologues: macaque CARMIL2 (98% identical), chimpanzee CARMIL2 (97% identical), dog CARMIL2 (88% identical), rabbit CARMIL2 (86% identical), pig CARMIL2 (85% identical), mouse Carmil2 (85% identical), rat Carmil2 (85% identical), guinea pig CARMIL2 (83% identical), tropical clawed frog CARMIL2 (31% identical), Drosophila melanogaster LRR (25% identical), Caenorhabditis elegans crml-1 (18% identical). Paralogues in human: CARMIL3 (31% identical), CARMIL1 (29% identical), PPP1R37 (10% identical), RNH1 (8% identical).
Diseases named in the same sentence as CARMIL2 in open-access papers:
CARMIL2 is named in the same sentence as 64 diseases in open-access papers, as found by Europe PMC text mining. Sharing a sentence is not in itself a finding about the gene and the disease. The quoted sentences say what the papers report.
smooth muscle tumor (6 papers, 2017 to 2025). A benign or malignant myomatous neoplasm arising from smooth muscle. "In this study, we describe homozygous loss-of-function CARMIL2 mutations in four human patients from two different families presenting with the highly unusual phenotype of disseminated EBV+ smooth muscle tumours (SMT)." (PMID 28112205, 2017). "Here, the authors identify human CARMIL2-deficiency as an autosomal recessive primary immunodeficiency disorder characterized by EBV+ smooth muscle tumours, CD28 co-signalling deficiency and impaired cytoskeletal dynamics." (PMID 28112205, 2017). "Management of CARMIL2 deficiency includes immunoglobulin replacement therapy, careful monitoring for EBV+ smooth muscle tumors, and considering HSCT as a potential cure." (PMID 39859044, 2025). "CARMIL2 deficiency is fully penetrant by the age of 10 yr and is characterized by numerous infections, EBV+ smooth muscle tumors, and mucocutaneous inflammation, including inflammatory bowel disease." (PMID 36515678, 2023). "Inherited CARMIL2 deficiency underlies infections, EBV+ smooth muscle tumors, and mucocutaneous inflammation." (PMID 36515678, 2023). "CARMIL2 deficiency causes defective CD28-mediated T cell co-stimulation, altered cytoskeletal dynamics, susceptibility to various infections and an Epstein–Barr virus-induced smooth muscle tumor (EBV-SMT)." (PMID 39873967, 2025). "CARMIL2 deficiency is a rare combined immunodeficiency (CID) characterized by defective CD28-mediated T cell co-stimulation, altered cytoskeletal dynamics, and susceptibility to Epstein Barr Virus smooth muscle tumors (EBV-SMTs)." (PMID 32625199, 2020). "Four patients with EBV+ disseminated smooth muscle tumors, and two homozygous LOF variants in the CARMIL2 gene exhibited these deficiencies without organ-specific autoimmunity." (PMID 39859044, 2025).
Immunodeficiency (5 papers, 2017 to 2025). Failure of the immune system to protect the body adequately from infection, due to the absence or insufficiency of some component process or substance. "In essence, CARMIL2 deficiency exhibits a diverse spectrum of clinical presentations, extending beyond known manifestations to include severe immunodeficiency and organ-specific autoimmune disorders." (PMID 41207919, 2025). "Within the field of primary immunodeficiencies, a unique subset has recently come to the forefront- combined immunodeficiency due to CARMIL2 (RLTPR) mutation." (PMID 41207919, 2025). "CARMIL2 deficiencies produce a combined immunodeficiency with defects in T-cell, B-cell, and NK cell function." (PMID 38535207, 2024). "With improved awareness of the CARMIL2 variant and expanded genetic screening, additional dogs with this immunodeficiency can be identified, thereby offering opportunities for further investigation of CARMIL2 deficiency in both humans and animals." (PMID 38535207, 2024). "This study reports the presence of a combined immunodeficiency caused by a CARMIL2 variant in three CKCSs with PCP or refractory Bordetella pneumonia." (PMID 38535207, 2024). "In summary, the phenotypic spectrum of CARMIL2 deficiency is broader than previously known, ranging from severe immunodeficiency to IBD and organ-specific autoimmunity." (PMID 33723309, 2021). "This case series underscores the clinical heterogeneity of CARMIL2-associated immunodeficiency and highlights the importance of genetic testing in patients with recurrent or atypical infections, particularly in populations with a high prevalence of consanguinity." (PMID 41207919, 2025). "The effect of CARMIL2 on T-cell activation, proliferation, and differentiation provides biological support for increased susceptibility to Pneumocystis in patients with CARMIL2 immunodeficiencies." (PMID 38535207, 2024). "Furthermore, genetic testing of CKCSs for the CARMIL2 variant can aid in clinical diagnosis of a PI and guide breeding practices, thus reducing the frequency of this specific immunodeficiency in the breed." (PMID 38535207, 2024). "Dogs could also be used to study novel therapeutic strategies for immunodeficiencies, such as IL-2 administration, which has been proposed for humans with CARMIL2 deficiencies." (PMID 38535207, 2024). "Therefore, both biological and clinical evidence suggests that human and canine patients affected by the CARMIL2 immunodeficiency might also be at increased risk for GI parasitism." (PMID 38535207, 2024). "Although only three dogs with the CARMIL2 variant have been identified, we anticipate that greater awareness of this PI among veterinarians, dog owners, and breeders will result in expanded genetic screening efforts and advance our understanding of the CARMIL2 variant and other immunodeficiencies." (PMID 38535207, 2024). "Our study marks a significant contribution to the understanding of CARMIL2-related immunodeficiency, particularly in the Palestinian region." (PMID 41207919, 2025). "Less than 100 human case reports of CARMIL2 immunodeficiencies have been documented, leaving our understanding of CARMIL2 variants and their biological implications incomplete." (PMID 38535207, 2024). "Our work expands the genotypic and phenotypic spectrum of CARMIL2 deficiency, which can present with either IBD or APS, aside from classic immunodeficiency manifestations." (PMID 33723309, 2021). "As the patient had a family history of CARMIL2 mutation and to rule out immunodeficiency, WES was ordered and confirmed SCID due to homozygote mutation C > T c." (PMID 41207919, 2025). "As the patient has a family history of CARMIL2 mutation and to rule out immunodeficiency, WES was ordered as well." (PMID 41207919, 2025). "Given the rarity of CARMIL2 immunodeficiencies in humans, data from naturally affected dogs might expand the understanding of biological and clinical outcomes for this condition in both species." (PMID 38535207, 2024).
Immunodeficiency (continued). "Overall, CARMIL2 should be included in the diagnostic work-up of patients with suspected monogenic IBD regardless of the age at disease onset and of the presence of overt clinical signs of immune deficiency." (PMID 33723309, 2021). "These CKCSs also suffered from non-respiratory clinical manifestations that parallel CARMIL2 immunodeficiencies in humans." (PMID 38535207, 2024). "CARMIL2 should be part of the diagnostic evaluation of patients with suspected monogenic IBD, even in the absence of obvious signs of immunodeficiency." (PMID 33723309, 2021). "The absence of the CARMIL2 variant in the 3 CKCSs and 15 other or unknown breed dogs with confirmed PCP suggests that additional PIs or acquired immunodeficiencies likely contribute to PCP susceptibility in dogs, much as in humans." (PMID 38535207, 2024). "Importantly, no mutations were detected in other known EV-associated or immunodeficiency-related genes, such as RHOH, IL7, CORO1A, STK4, DOCK8, or CARMIL2, supporting the notion that the identified TMC6 and TMC8 variants may represent the primary genetic contributors in this case." (PMID 40534698, 2025).
inflammatory bowel disease (4 papers, 2021 to 2025). A spectrum of small and large bowel inflammatory diseases of unknown etiology. "GI manifestations were reported in 55/87 (63%) CARMIL2-deficient individuals, of whom 19/87 (22%) had histologically confirmed inflammatory bowel disease (IBD)." (PMID 36515678, 2023). "Recently, biallelic loss-of-function (LoF) variants of CARMIL2 have been linked to very early onset inflammatory bowel disease (IBD) or IBD-like inflammatory gastrointestinal disorder, with or without clinical manifestations of immunodeficiency." (PMID 33723309, 2021). "CARMIL2 is required for CD28-mediated co-stimulation of NF-κB signaling in T cells and its deficiency has been associated with primary immunodeficiency and, recently, very early onset inflammatory bowel disease (IBD)." (PMID 33723309, 2021). "However, none of our patients experienced inflammatory bowel disease (IBD), or chronic diarrhea, which have often been reported in other patients with CARMIL2 mutations." (PMID 41207919, 2025).
combined immunodeficiency (3 papers, 2018 to 2025). A broad classification of inherited disorders presenting at birth that affect both the cell-mediated and humoral aspects of the immune response. "Combined immunodeficiency due to CARMIL2 mutations is a rare autosomal recessive primary immunodeficiency characterized by impaired T-cell activation and function, leading to diverse clinical manifestations." (PMID 41207919, 2025).
COVID-19 (3 papers, 2023 to 2024). A disease caused by infection with severe acute respiratory syndrome coronavirus 2. "Contrary to CARMIL2 and CCR7, consistent expression of NIBAN3, also known as B-cell novel protein 1 (BCNP1), in SAT under consideration of infection with and without vaccination lacks direct associations with obesity, T2D, or COVID-19." (PMID 38474155, 2024).
Failure to thrive (3 papers, 2023 to 2024). Failure to thrive (FTT) refers to a child whose physical growth is substantially below the norm. "Failure to thrive was noted in 46/84 (55%) CARMIL2-deficient individuals and was positively associated with GI tract involvement (r = 0.31, P < 0.01)." (PMID 36515678, 2023).
molluscum contagiosum (3 papers, 2016 to 2025). A common, benign, usually self-limited viral infection of the skin and occasionally the conjunctivae by a poxvirus (molluscum contagiosum virus). "The majority of reported symptoms associated with the CARMIL2 mutation involves recurrent respiratory system infections, cutaneous warts, psoriatic rash, recurrent condyloma, molluscum contagiosum, solar urticaria, and different forms of dermatitis." (PMID 41207919, 2025). "A review of previous literature on CARMIL2 mutations reveals that the clinical manifestations differ depending on the specific mutation, with recurrent pulmonary infections, dermatitis, skin abscesses, molluscum contagiosum, warts, and signs of EBV infection being the most common features." (PMID 41207919, 2025).
Primary immunodeficiency (3 papers, 2021 to 2025). "Currently, there are no targeted therapies that directly address the immune pathway dysfunction caused by CARMIL2 mutation, making management of this primary immunodeficiency markedly limited." (PMID 41207919, 2025).
actinopathies (2 papers, 2024 to 2025). "Rescue of T-cell activation by the addition of exogenous IL-2 in actinopathies was previously reported by our group and others in CARMIL2 deficiency and WAS protein knockout mouse model." (PMID 40748410, 2025). "This contrasts with the deficiency of other actinopathy-associated proteins such as WASP, CARMIL2 for which normal ZAP70 activation was reported, however TCR signaling beyond ZAP70 has been shown to be impaired in those deficiencies." (PMID 39120629, 2024). "NK cell function defects have been described for other actinopathies, including DOCK8, WASP, WIP, Arp2/3 and perhaps CARMIL2." (PMID 39120629, 2024).
Atopic dermatitis (2 papers, 2023). "Atopic dermatitis affected 60/87 (69%) CARMIL2-deficient individuals within the first 2 yr of life." (PMID 36515678, 2023).
Autoimmunity (2 papers, 2018 to 2021). The occurrence of an immune reaction against the organism's own cells or tissues. "Moreover, CARMIL2 interactome include DOCK8, that is mutated in patients presenting with autoimmune disorders, eczema and compromised Treg function." (PMID 33723309, 2021). "Notably, CARMIL2-deficient mice and humans did not develop any obvious organ-specific autoimmune disorder, despite a reduction in Tregs8,9." (PMID 33723309, 2021). "CARMIL2-deficient patients have a normal production of TH2 cytokines, but a reduced secretion of TH1, as well as TH17 effector cytokines, and therefore the strong decrease in Treg numbers does not result in the development of autoimmunity." (PMID 29867948, 2018).
bronchiectasis (2 papers, 2023 to 2025). Segmental, irreversible dilation of the bronchial tree resulting in the accumulation of secretions which leads to obstruction. "Bronchiectasis was reported in 12/87 (14%) CARMIL2-deficient individuals." (PMID 36515678, 2023).
Chronic diarrhea (2 papers, 2024 to 2025). The presence of chronic diarrhea, which is usually taken to mean diarrhea that has persisted for over 4 weeks. "The CKCSs with the CARMIL2 nonsense variant reported here also exhibited several of these clinical features, including chronic diarrhea, allergic skin disease, skin abscesses, and oral mucocutaneous lesions, with each reported in one or more affected dogs." (PMID 38535207, 2024). "In addition to respiratory infection, several clinical parallels have been observed between these dogs and the reported human cases of CARMIL2 deficiencies, including chronic diarrhea, allergic skin disease, mucocutaneous lesions, autoimmune disorders, GI parasitism, and abscess formation." (PMID 38535207, 2024).
cutaneous T cell lymphoma (2 papers, 2018 to 2025). "A CARMIL2 point mutation denoted as CARMIL2 p.Q575E and corresponding to a nonconservative substitution of the glutamine residue found at position 575 by a glutamic acid has been identified in 3% of human cutaneous T cell lymphoma and acute T cell leukemia." (PMID 40402149, 2025). "Intriguingly CARMIL2 can also work in a dominant mode, as a gain-of-function mutation (Q575E) has been linked to cutaneous T cell lymphoma, selectively upregulating the NF-κB pathway and causing activated T cells to significantly increase their IL-2 production." (PMID 29479355, 2018).
dermatitis (2 papers, 2018 to 2025). An inflammatory process affecting the skin. "Here, we utilized whole exome sequencing (WES) and other assays to genetically and functionally characterize three consanguineous multiplex Saudi families with CARMIL2 mutations, presenting with dermatitis, recurrent skin abscesses and chest infections." (PMID 29479355, 2018).
eczema (2 papers, 2021 to 2025). "Additionally, skin manifestations have been described in the majority of CARMIL2-deficient patients, and eczema is part of other monogenic APSs9–14,17,18,30." (PMID 33723309, 2021).
esophageal disease (2 papers, 2018 to 2023). "Bacterial skin abscesses occurred in 26/87 (30%), and chronic mucocutaneous candidiasis, presenting as oral thrush, intertrigo, onychomycosis, and/or esophagitis, occurred in 24/87 (28%) CARMIL2-deficient individuals." (PMID 36515678, 2023). "A striking feature of our CARMIL2-deficient patients is their esophageal disease as was observed in five patients, mostly secondary to Candida infection, eosinophilic or nonspecific active esophagitis." (PMID 29479355, 2018).
fibrosarcoma (2 papers, 2017 to 2018). A malignant mesenchymal fibroblastic neoplasm affecting the soft tissue and bone. "CARMIL2 has been shown to provide a functional link between vimentin intermediate filaments and membrane-associated actin networks during lamellipodia formation, cell migration and invadopodia-mediated matrix degradation in fibrosarcoma cells." (PMID 28112205, 2017). "In fibrosarcoma cells CARMIL2 provides the molecular link between vimentin intermediate filaments and actin, thereby playing a role in cell polarity, lamellipodial assembly, and the creation of protrusions that allow cellular migration." (PMID 29479355, 2018).
allergic asthma (1 paper, 2023). A asthma with a basis in a pathological type I hypersensitivity reaction. "Food allergies were reported in 12/87 (14%) and allergic asthma was diagnosed in 33/87 (38%) CARMIL2-deficient individuals." (PMID 36515678, 2023).
autoimmune disorders (1 paper, 2024). "Impaired regulatory T-cell development can increase the risk of autoimmune disease in human patients with CARMIL2 deficiencies, and one CKCS also suffered from MMM, an inflammatory myopathy that occurs when autoantibodies against 2M myofibers are produced." (PMID 38535207, 2024).
CMV pneumonia (1 paper, 2023). "In addition to CMV pneumonia, five cases of CMV-induced retinitis and four cases of CMV colitis were reported, so clinical CMV disease was observed in 11/87 (13%) CARMIL2-deficient individuals." (PMID 36515678, 2023).